CRP (C-reactive protein)
Diseases named in the same sentence as CRP in open-access papers (continued):
Sharing a sentence is not in itself a finding about the gene and the disease.
bacterial infection (continued). "However, the exact cut-off is still disputable and many different CRP values were suggested to indicate a bacterial infection (such as 10, 20, 40, 60 and 100 mg/L)." (PMID 34863104, 2021). "Elevated serum CRP as well as ferritin levels might have a clinical correlation with secondary bacterial infection, contributing to poor prognosis." (PMID 33628256, 2021). "Therefore, CRP was considered to be able to distinguish between viral and bacterial infections in the 1990s." (PMID 34583675, 2021). "The observation that aHUS is often preceded by bacterial infections and that a substantial percentage of C3G patients presents with high titers of antistreptolysin-O make CRP a strong candidate for being a trigger of complement dysregulation in carriers of C2 GoF mutations." (PMID 34899688, 2021). "Recognizing that children with PHGS may manifest prolonged high fever, leukocytosis, and a high serum CRP level that mimics bacterial infections may help clinicians to avoid the unnecessary prescription of antibiotics." (PMID 33081701, 2020). "This suggests age-related WBC and PN migration with impaired recruitment from the bone marrow into the circulation in younger children in spite of an important inflammatory response to the bacterial infection reflected by the induction of high levels of CRP in the liver." (PMID 32248803, 2020). "Procalcitonin is more specific for bacterial infections than CRP or white cell count." (PMID 32766268, 2020). "We showed that the CRP level, WBC count, and IgM level, other than the PCT level, do not provide sufficient diagnostic accuracy, either alone or in combination, for the detection of early-onset bacterial infections." (PMID 33081061, 2020). "The other predictors (CTP higher than 9, CRP concentration greater than 9.2 mg/L, MELD score exceeding 18 points, or NLR higher than 3.957) had a lower AUC; however, they were still significantly associated with a higher bacterial infection risk." (PMID 32155772, 2020). "Active inflammation and bacterial infection leads to a CRP level from 40 to 200 mg/L." (PMID 33266250, 2020). "CRP is synthesized mainly in the liver during the acute phase of a bacterial infection." (PMID 33081061, 2020). "The serum levels of CRP may increase from 100 to 1000 times in response to bacterial infections or other inflammatory conditions and concentrations correlate with severity of illness." (PMID 33419284, 2020). "Elevated levels of CRP usually indicate bacterial infection." (PMID 32134948, 2020). "However, PCT level was the best predictor of bacterial infections, with an area under the curve (AUC) of 0.874, followed by CRP level (AUC = 0.855) and NLR (AUC = 0.792) (p < 0.0001)." (PMID 32908505, 2020). "Interestingly, an organ system with frequent contact to microorganisms (respiratory tract), which is known to present with high CRP values in the case of bacterial infection, was underrepresented in our study." (PMID 32434519, 2020). "Our results support the finding of high CRP levels in children with bacterial infection." (PMID 32429293, 2020). "CRP seemed to be regarded as a superior test that could confirm or exclude significant bacterial disease." (PMID 32031035, 2020). "Its low specificity and inability to differentiate bacterial infections from non-infectious causes of inflammation make CRP of limited diagnostic value." (PMID 32070390, 2020). "It has a higher diagnostic accuracy than CRP to differentiate bacterial infections from noninfectious causes and viral infections in patients hospitalized for suspected infectious diseases." (PMID 32398008, 2020). "We excluded all patients that had developed an additional bacterial infection from this analysis as this might have affected the CRP values." (PMID 33322797, 2020).
bacterial infection (continued). "The calculated MELD score, CTP, NLR, LMR, AAR, monocyte count, and C-reactive protein (CRP) concentration were also related to the bacterial infection prevalence, and mortality areas under the curve (AUC) were 0.629, 0.687, 0.606, 0.715, 0.610, 0.648, and 0.685, respectively." (PMID 32155772, 2020). "Thus, in the present study, we first evaluated the diagnostic value of PCT, CRP, and NLR compared with conventional biomarkers such as WBC and NEU counts in determining bacterial infections in febrile NNLCPs." (PMID 32908505, 2020). "•C-reactive protein was significantly increased in cases of bacterial infections." (PMID 32437937, 2020). "The increase of LDH and CRP indicated that the injury of the body was severe and may be complicated with bacterial infection which affected the prognosis." (PMID 33382747, 2020). "Furthermore, episodes with insufficient RNA for sequencing and ANC < 0.1 × 109/L had more days on antibiotics, higher CRP, and a trend towards more bacterial infections (15% vs. 5%) compared with the episodes with sufficient RNA for sequencing." (PMID 32722616, 2020). "Some of the studies advise to use a combination of biomarkers as the sensitivity and specificity might increase than using a biomarker alone Nevertheless, WBC and CRP remain the most widely used biomarkers in bacterial infection diagnostics." (PMID 30974881, 2019). "Nevertheless, to the best of the authors’ knowledge, there are no reports about the diagnostic properties of PCT and CRP for bacterial infection in GPP patients." (PMID 31777354, 2019). "Raman spectroscopy was also used to identify and quantify the C-reactive protein (CRP) concentration in blood plasma, a sensitive biomarker of inflammation caused by bacterial infection, typically determined by time-consuming and high-priced immunoassays techniques." (PMID 31489927, 2019). "Briefly, C-reactive protein (CRP) is an acute phase reactant synthesized by the liver in response to cytokines, such as interleukin-6, released by macrophages and adipocytes in response to inflammatory conditions from bacterial infections." (PMID 30987144, 2019). "Our data, although limited, suggest that CRP or PCT concentrations may help discriminate invasive bacterial infections in patients with neurological disorders in tropical settings and that normal CRP values could assist in withholding antibiotics." (PMID 31664120, 2019). "On the other hand, high CRP or PCT concentrations (as conventionally defined) had positive likelihood ratios (i.e. power to rule-in invasive bacterial infections) superior to that of classic clinical features and similar to that of an elevated WBC count in blood." (PMID 31664120, 2019). "On the other hand, and maybe more interestingly, a normal CRP value made a diagnosis of invasive bacterial infection very unlikely in our observations and was independently associated with favorable outcome." (PMID 31664120, 2019). "The risk of serious bacterial infection in patients in primary care without clear clinical danger signs is low, and the majority of patients in the trial had low CRP concentrations on day 0 (<20 mg/L in 72% of patients and <40 mg/L in 86%)." (PMID 30554748, 2019). "The C-reactive protein (CRP) value was monitored throughout the study and used as an indicator of unrelated inflammatory conditions (e.g., viral or bacterial infections), which could affect the evaluated blood parameters." (PMID 30745882, 2019). "CRP is an acute phase reactant whose levels elevate during inflammatory processes occurring in the body; elevated serum CRP levels can also be detected in the conditions not caused by bacterial infection." (PMID 29675434, 2018). "However, in laboratory findings, bacterial infection patients displayed high leukocyte counts and C-reactive protein (CRP) (P < 0.05)." (PMID 29623264, 2018). "Thirty percent of mothers had CRP above the threshold of 40 mg/L, indicating bacterial infection." (PMID 30223547, 2018).
bacterial infection (continued). "Theoretically, the CRP value could be decreased by using antibiotics to treat the bacterial infection." (PMID 29311572, 2018). "In general, a higher CRP level may indicate a more severe bacterial infection or stronger immune response." (PMID 30416990, 2018). "CRP and procalcitonin are the most widely used markers for bacterial infections." (PMID 30559815, 2018). "Additionally, the traditional biomarkers of bacterial infection, procalcitonin and C-reactive protein levels in blood fluctuated during the disease process, but the two indicators of fatal cases with H7N9-A." (PMID 30551738, 2018). "Serum PCT levels show a positive correlation with CRP levels in patients with bacterial infection." (PMID 30647802, 2018). "A systematic review published by Markanday in 2015 compared serum PCT versus CRP as markers for bacterial infection and showed that, compared to CRP, S–PCT had a higher sensitivity and specificity for differentiating bacterial from noninfectious causes of inflammation." (PMID 29891780, 2018). "Furthermore, CRP is elevated in more than 90% of acute spondylodiscitis cases and is a sensitive marker for bacterial infection." (PMID 29356895, 2018). "C-reactive protein (CRP) as a biomarker of bacterial infection is one of these interventions, and new point-of-care testing (POCT) solutions are hoped to become an additional tool for low- and middle-income countries (LMICs) to limit the growing problem of AMR." (PMID 29499522, 2018). "As may be expected from a bacterial infection, levels of leukocytes and C-reactive protein had increased—although the subsequent increase of both was partly associated with the surgery." (PMID 29511694, 2018). "Thus, the diagnostic performance of CRP dropped, whereas the performance of HNL increased considerably, which is a strong support to the specificity of HNL as a reflection of bacterial infections." (PMID 28468981, 2017). "Finally, although the CRP levels were moderately elevated in our study, the mean procalcitonin level was only 0.35 μg/L, confirming that a bacterial infection was unlikely." (PMID 28114362, 2017). "However, there are considerably varying data regarding the sensitivity and specificity of CRP as a marker in predicting bacterial infections." (PMID 28451028, 2017). "In daily clinical practice a CRP value below 20 mg/L is usually considered not to be associated with a bacterial infection." (PMID 28526094, 2017). "This lack of an increase may be the result of excluding patients with presumptive bacterial infections, such as a low CRP level, because LPS is the main inducer of IL-1β synthesis." (PMID 29017522, 2017). "Copeptin, a vasopressin surrogate molecule for PCT, peptide precursor of calcitonin rising in bacterial infection, or proADM, an adrenal gland molecule, are better mortality predictive markers than long-standing inflammatory parameters such as CRP or total WBC at admission." (PMID 28301543, 2017). "Measurement of CRP is considered to be of particular value as an indicator of bacterial infection." (PMID 28486434, 2017). "Therefore, all AECOPD patients are suggested for undergoing serum PCT and CRP levels detection before treatment to help the diagnosis of bacterial infection and guide the reasonable use of antibacterial drugs." (PMID 28811772, 2017). "WBC and CRP levels had limited value in identifying children with bacterial infections." (PMID 27935664, 2017). "The CRP reduction may also reflect removal (or resolution) of the inciting event (e.g. viral or bacterial infection)." (PMID 28328968, 2017). "One possible advantage of PCT over CRP is that it appears to have specificity for bacterial infection, and therefore may play a role in recognition of a bacterial infection prior to culture results becoming available." (PMID 29104224, 2017).
bacterial infection (continued). "Moreover, in most cases, the results of routine laboratory tests, including white blood cell (WBC) count and serum C-reactive protein (CRP) levels, tend to overlap, making differentiation between viral and bacterial infection impossible." (PMID 27439403, 2016). "The acute phase response is a complex systemic response to e.g. bacterial infection, tissue injury, and trauma characterized by up- and down regulation of blood levels of a variety of proteins, termed acute phase proteins, such as C-reactive protein (CRP) and Serum Amyloid A (SAA)." (PMID 26792395, 2016). "Regarding probable bacterial infections, CRP level was the best predictor." (PMID 27439403, 2016). "Also, serum C-reactive protein (CRP) concentration was less than 5 mg/dL at the time of diagnosis in 5 out of 8 episodes of invasive bacterial infections within 24 hours after onset." (PMID 26825884, 2016). "Although specific situations may exist where serum CRP indeed could be helpful for predicting presence of bacterial infection, as suggested in dogs with respiratory disease, this is not generally applicable." (PMID 27793205, 2016). "For many years, it has been shown that only extremely high CRP serum levels are associated with bacterial disease and negative prognosis, whereas in many cases, these values do not allow the real etiology of the disease to be determined." (PMID 27439403, 2016). "We are aware that the low CRP-levels (≤ 40 mg/L) tested within 24 hours after admission used in our study, may underestimate the occurrence of a bacterial infection or bacterial super-infection." (PMID 26964038, 2016). "For many years, it has been shown that only extremely high CRP serum levels are associated with bacterial disease and a negative prognosis, whereas in many cases, such values do not permit an estimate of the real etiology of the disease." (PMID 27846213, 2016). "In clinical settings, white blood cell counts, C-reactive protein and procalcitonin could be used to facilitate the diagnosis of bacterial infection." (PMID 27240351, 2016). "CRP and leukocyte levels may be markers of significant bacterial infection providing a rationale for antibiotic treatment." (PMID 27104349, 2016). "CRP was the most frequently studied host biomarker in this review and the majority of these studies (33/36; 92%) reported statistically significant differences in CRP levels measured in patients with bacterial and those with non-bacterial infections." (PMID 27486746, 2016). "In addition, bacterial infections were unlikely because most children had received one or more conjugated pneumococcal vaccinations, and only patients with maximal CRP levels less than 100 mg/L were included." (PMID 27171557, 2016). "C-reactive protein (CRP) is a ring-shaped pentameric protein found in blood plasma, whose initial role as a pattern recognition molecule may have been to defend against bacterial infection." (PMID 26225981, 2015). "CRP is used as an inflammation biomarker, particularly for bacterial infections." (PMID 26247033, 2015). "Reviewing several systematic analyses of CRP shows that low cutoff values of CRP demonstrate high sensitivity and low specificity for detecting bacterial infection, whereas high cutoff values of CRP show low sensitivity and high specificity for detecting bacterial infection." (PMID 26672961, 2015). "Elevated CRP levels are suggestive of a bacterial infection, but similar levels may be observed in patients with some viral strains (e.g., adenovirus and influenza), and inflammatory diseases." (PMID 25785720, 2015). "Furthermore, it has been shown that inflammatory signs can be masked by immunosuppressants or corticosteroid and render C-reactive protein (CRP) inconsistently reliable as a biomarker for bacterial infection in this setting." (PMID 26446077, 2015). "Furthermore, CRP concentration or WBC count have been shown to increase in pediatric transplantation patients with acute rejection or bacterial infection." (PMID 26275220, 2015).
bacterial infection (continued). "Because CRP is the end product of cytokine response after tissue injury, it is likely that extremely preterm or very low birth weight infants have less pronounced immunomodulatory or pre-inflammatory proteins after bacterial infection." (PMID 26259626, 2015). "The rise in CRP usually corresponds with the extent of bacterial infection." (PMID 26672961, 2015). "High‐sensitivity CRP is utilized in clinical practice as an auxiliary biomarker of COPD exacerbation to evaluate whether bacterial infection is involved in the exacerbation and to predict whether antibiotics may be useful for the treatment." (PMID 24994897, 2014). "However, the combination of CRP, neutrophil and IG levels had the highest specificity for predicting bacterial infections." (PMID 24764729, 2014). "Although our results should be confirmed in a prospective study including larger number of patients, we believe that IG, neutrophil and CRP values may guide physicians to make a distinction between viral and bacterial infections." (PMID 24764729, 2014). "Most authors concluded that CRP >40 mg/dL indicates severe bacterial infections." (PMID 24764729, 2014). "The significance of CRP measurement in preoperative patient assessment is recognized to be limited, while, for instance, there was a report showing the usefulness of CRP in patients with bacterial infections." (PMID 25548797, 2014). "However the time of the transiently increased CRP concentration is consistent with the onset of bacterial infection in irradiated-wounded mice." (PMID 24175013, 2013). "In this regard, when patients suffer from inflammation, as evidenced by a high CRP level, the procalcitonin level can be used to distinguish bacterial infections from other pathogeneses with relatively high specificity, enabling prompt and correct diagnosis of patients." (PMID 23843799, 2013). "Thus, a study was published in a pediatric cohort, showing the great interest, in terms of avoiding useless tests, of using CRP RDT (microCRP) for the diagnosis of bacterial infection in children." (PMID 24069477, 2013). "During the febrile phase of PFAPA, the immunological response may mimic that of bacterial infections with high levels of C-reactive protein (CRP)." (PMID 24134207, 2013). "In our setting, CRP is ordered routinely on children presenting with symptoms and/or signs suggestive of acute infection as a baseline test to help discriminate viral from bacterial infection." (PMID 22943554, 2012). "On the other hand, PCT and CRP are strongly induced by endotoxin, which may explain their enhanced usefulness for the diagnosis of bacterial infection." (PMID 22221662, 2012). "C-reactive protein (CRP) is widely used to detect bacterial infection in children." (PMID 22943554, 2012). "WBC count and CRP were elevated in patients with suspected bacterial infection." (PMID 21702977, 2011). "Nevertheless, we cannot exclude that CRP production is increased in these patients by bacterial infections that could also favor IL-6 production." (PMID 22032643, 2011). "Analysis of CRP is frequently used to discriminate viral from bacterial infections." (PMID 21521505, 2011). "However, these indicators lack both sensitivity and specificity and there is still a need for more accurate measures of bacterial infection; devices measuring acute phase proteins such as C-reactive protein or procalcitonin merit further research." (PMID 21978238, 2011). "C-reactive protein (CRP) is an excellent marker for established neonatal bacterial infections." (PMID 22164179, 2011). "We, therefore, tested whether the predictive value of suPAR was equal or superior to classical markers of inflammation and bacterial infection by using ROC curve analyses comparing suPAR with CRP, procalcitonin (PCT) and white blood cell count." (PMID 21324198, 2011). "A high CRP value (>100 mg/L) can indicate a severe bacterial infection." (PMID 20011658, 2009).